MORF4 (mortality factor 4 (pseudogene))
Synonyms: formerly SEN; SEN1
Gene: Processed pseudogene on chromosome 4 (173,615,936 to 173,616,906, reverse strand). Ensembl gene ENSG00000234801.
Diseases named in the same sentence as MORF4 in open-access papers:
MORF4 is named in the same sentence as 6 diseases in open-access papers, as found by Europe PMC text mining. Sharing a sentence is not in itself a finding about the gene and the disease. The quoted sentences say what the papers report.
colorectal carcinoma (1 paper, 2012). A malignant epithelial neoplasm that arises from the colon or rectum and invades through the muscularis mucosa into the submucosa. "MORF4 is up-regulated in high degree microsatellite instability colorectal carcinoma." (PMID 23056603, 2012).
hepatocellular carcinoma (1 paper, 2021). A malignant tumor that arises from hepatocytes. "This study investigated the expression change, prognostic values, and potential regulatory mechanisms of mortality factor on chromosome 4 (MORF4)-related gene-binding protein (MRGBP) in hepatocellular carcinoma (HCC)." (PMID 33761715, 2021).
cancer (1 paper, 2023). A tumor composed of atypical neoplastic, often pleomorphic cells that invade other tissues. "MORF4L1 is a member of a gene family related to MORF4 and is involved in cancer cell senescence." (PMID 37365518, 2023).
MORF4 also shares sentences with these, for which no sentence is quoted: bladder cancer (1 paper); co-infection (1); infection (1).